HIPK2 (homeodomain interacting protein kinase 2)
Description:
Acts as a corepressor of several transcription factors, including SMAD1 and POU4F1/Brn3a and probably NK homeodomain transcription factors. Involved in the response to hypoxia by acting as a transcriptional co-suppressor of HIF1A. Mediates transcriptional activation of TP73. In response to TGFB, cooperates with DAXX to activate JNK. Negative regulator through phosphorylation and subsequent proteasomal degradation of CTNNB1 and the antiapoptotic factor CTBP1. In the Wnt/beta-catenin signaling pathway acts as an intermediate kinase between MAP3K7/TAK1 and NLK to promote the proteasomal degradation of MYB. Phosphorylates CBX4 upon DNA damage and promotes its E3 SUMO-protein ligase activity. Activates CREB1 and ATF1 transcription factors by phosphorylation in response to genotoxic stress. In response to DNA damage, stabilizes PML by phosphorylation. Promotes angiogenesis, and is involved in erythroid differentiation, especially during fetal liver erythropoiesis. Phosphorylation of RUNX1 and EP300 stimulates EP300 transcription regulation activity. Triggers ZBTB4 protein degradation in response to DNA damage. In response to DNA damage, phosphorylates DAZAP2 which localizes DAZAP2 to the nucleus, reduces interaction of DAZAP2 with HIPK2 and prevents DAZAP2-dependent ubiquitination of HIPK2 by E3 ubiquitin-protein ligase SIAH1 and subsequent proteasomal degradation. Modulates HMGA1 DNA-binding affinity. In response to high glucose, triggers phosphorylation-mediated subnuclear localization shifting of PDX1. Involved in the regulation of eye size, lens formation and retinal lamination during late embryogenesis.
Synonyms: PRO0593
Tractability: Small molecule: a structure with a bound ligand is known; a high-quality ligand is known; it belongs to a druggable protein family. PROTAC: UniProt records ubiquitination sites on it; ubiquitination databases record sites on it; a small molecule that binds it is known.
Target class: CMGC protein kinase group; CMGC protein kinase HIPK subfamily; Enzyme; Kinase; CMGC protein kinase DYRK family; Protein Kinase
Chemical probes: CVM-6-139-1 (high quality), PD081021
Gene: Protein-coding gene on chromosome 7 (139,561,570 to 139,777,998, reverse strand). Ensembl gene ENSG00000064393.
Subcellular location: Nucleus, PML body; Cytoplasm; Cytoplasm, Stress granule
Subcellular location (Human Protein Atlas): Nucleoplasm
Pathways (Reactome):
Gene expression (Transcription): RUNX1 interacts with co-factors whose precise effect on RUNX1 targets is not known; YAP1- and WWTR1 (TAZ)-stimulated gene expression
Metabolism of proteins: SUMOylation of transcription cofactors
Muscle contraction: Physiological factors
Gene Ontology:
Molecular function: protein binding; protein kinase activity; protein serine kinase activity; protein serine/threonine kinase activity; RNA polymerase II-specific DNA-binding transcription factor binding; SMAD binding; transcription corepressor activity; virion binding; transcription coactivator activity; ATP binding
Biological process: negative regulation of BMP signaling pathway; negative regulation of ubiquitin-dependent protein catabolic process; peptidyl-serine phosphorylation; positive regulation of angiogenesis; positive regulation of JNK cascade; positive regulation of transcription by RNA polymerase II; positive regulation of transforming growth factor beta receptor signaling pathway; protein phosphorylation; SMAD protein signal transduction; cellular response to hypoxia; epigenetic regulation of gene expression; erythrocyte differentiation; eye development; intrinsic apoptotic signaling pathway; PML body organization; regulation of cell cycle; smoothened signaling pathway; embryonic camera-type eye morphogenesis; embryonic retina morphogenesis in camera-type eye; iris morphogenesis; lens induction in camera-type eye; negative regulation of transcription by RNA polymerase II; and 2 more
Cellular component: cytoplasm; cytoplasmic stress granule; nuclear body; nucleoplasm; nucleus; PML body; RNA polymerase II transcription regulator complex
Genetic constraint (gnomAD): Loss-of-function variants: 25 observed, 104.84 expected, observed/expected ratio (o/e) 0.24, 90% interval 0.17 to 0.33. The upper end of that interval is the gene's LOEUF score, 0.33, which puts it in group 1 of 6, group 1 being the genes least tolerant of losing a copy. Missense variants: 1,247 observed, 1,592.6 expected, observed/expected ratio (o/e) 0.78, 90% interval 0.75 to 0.82. Synonymous variants: 627 observed, 637.82 expected, observed/expected ratio (o/e) 0.98, 90% interval 0.92 to 1.05.
Homologues: Orthologues: chimpanzee HIPK2 (99% identical), macaque HIPK2 (99% identical), guinea pig HIPK2 (97% identical), dog HIPK2 (97% identical), rabbit HIPK2 (97% identical), mouse Hipk2 (97% identical), rat Hipk2 (96% identical), pig HIPK2 (94% identical), zebrafish hipk2 (81% identical), tropical clawed frog hipk2 (79% identical), Drosophila melanogaster mnb (14% identical), Caenorhabditis elegans mbk-1 (13% identical), and 2 more. Paralogues in human: HIPK1 (64% identical), HIPK3 (52% identical), HIPK4 (20% identical), DYRK1A (15% identical), DYRK2 (14% identical), DYRK1B (13% identical), DYRK3 (13% identical), DYRK4 (13% identical), CLK1 (10% identical), CLK4 (10% identical), CLK2 (10% identical), CLK3 (10% identical).
Diseases named in the same sentence as HIPK2 in open-access papers:
HIPK2 is named in the same sentence as 132 diseases in open-access papers, as found by Europe PMC text mining. Sharing a sentence is not in itself a finding about the gene and the disease. The quoted sentences say what the papers report.
colon carcinoma (17 papers, 2009 to 2024). "Results from next generation sequencing (NGS) analysis revealed that high HIPK2 expression significantly associates with risk of colon cancer recurrence." (PMID 39062921, 2024). "In vitro studies with colon cancer cell lines, using siRNA, showed that HIPK2 silencing is associated with increased PGE2 biosynthesis that was profoundly suppressed by the cPLA2 inhibitor." (PMID 39062921, 2024). "Further studies are necessary to demonstrate that hypothesis and the underlying molecular mechanisms of the NRF2/HIPK2 interplay in colon cancer, but also in other types of cancers, tilting the death/survival outcome." (PMID 39062921, 2024). "Indeed, Hipk2−/− mice are more susceptible to skin chemical carcinogenesis, and HIPK2 expression is down-regulated in breast, thyroid, and colon carcinomas." (PMID 34361060, 2021). "The aim of this review is to assess the role of HIPK2 in colon cancer and the underlying molecular pathways for a better understanding of its involvement in colon cancer carcinogenesis and response to therapies, which will likely pave the way for novel colon cancer therapies." (PMID 39062921, 2024). "MC38 colon carcinoma cells were subcutaneously injected into WT and HIPK2+/− mice, and the authors found that tumors grow more rapidly in HIPK2+/− mice and that, surprisingly, the percentage of macrophages is increased in the tumors of HIPK2+/− mice." (PMID 39062921, 2024). "Analysis of datasets showed PRNT upregulation in OXA-resistant colon cancer along with downregulation of HIPK2." (PMID 39062921, 2024). "High cytosolic phospholipase A2 (cPLA2) expression and PGE2 production;HIPK2 represses cPLA2 promoter activity;Increased in vivo tumor growth of xenografts from HIPK2-depleted colon cancer cells;Inverse correlation between HIPK2 expression and Dukes stage." (PMID 39062921, 2024). "In this regard, the aim of this review is to assess the role of the “bona fide” oncosuppressor homeodomain interacting protein kinase-2 (HIPK2) in colon cancer progression and response to therapies." (PMID 39062921, 2024). "In only one study, high HIPK2 expression in colon cancer tissues was found to correlate with tumor progression and TNM stages, although the molecular mechanisms were not completely unveiled." (PMID 39062921, 2024). "Immunohistochemistry (IHC) analysis of 100 colon tumor samples and 20 normal intestinal tissues displayed that HIPK2 expression inversely correlates with Dukes stage and depth of cancer invasion." (PMID 39062921, 2024). "In colon cancer tissues, HIPK2 mRNA expression was found to be significantly downregulated compared to the adjacent normal tissues and, mechanistically, exomiR-1229 was found to target the HIPK2 3’UTR." (PMID 39062921, 2024). "As a proof of principle, analysis of HIPK2 mRNA expression in human colon cancers showed that it tended to correlate inversely with the Dukes staging of the tumors, in agreement with the Zhou and colleagues’ study." (PMID 39062921, 2024).
colon carcinoma (continued). "Below is a summary of the studies that, up to now, have evaluated the HIPK2 expression in colon cancer tissues, genomic data sets and cell lines, with a focus on the interaction with molecular pathways involved in cancer progression and response to therapies." (PMID 39062921, 2024). "For these reasons, HIPK2 is becoming an appealing molecule in the colon cancer field, deserving in-depth analysis in future studies, for further understanding of colon cancer development and response to therapies." (PMID 39062921, 2024). "Through the production of TMAs of cancer samples from a retrospective series of 270 stage I to IV patients with colon cancer, the HIPK2 protein expression was evaluated by IHC analyses." (PMID 39062921, 2024). "Mechanistically, conditioned media of HIPK2-silenced colon cancer cells induced autophagy in fibroblasts that reduced caveolin-1 levels, a hallmark of the aggressive CAF phenotype in cancer patients." (PMID 39062921, 2024). "The expression of HIPK2 was then evaluated in primary tumor specimens of human colon cancer, with particular regard to post-operative cancer recurrence, metastasis and malignancy grades." (PMID 39062921, 2024). "As a proof-of-principle of the HIPK2/HIIF-1/VEGF regulation, conditioned media from HIPK2 knockdown colon cancer cells has been shown to enhance in vitro tube formation of HUVEC." (PMID 39062921, 2024). "It was shown that HIPK2-modulated pathways derived from colon cancer cells depleted of HIPK2 function are involved in fibroblast transdifferentiation CAF-like." (PMID 39062921, 2024). "Mechanistically, PRNT regulates HIPK2 mRNA expression in colon cancer by sponging ZNF184 transcription factor." (PMID 39062921, 2024). "The knockdown of endogenous HIPK2 in colon cancer cells augments the stability of β-catenin and the expression of β-catenin target genes, stimulating proliferation, increased wound healing and in vivo tumor growth." (PMID 39062921, 2024). "Summary of the HIPK2 expression in colon cancer tissues and cell lines along with the biological and molecular effects and the specific references." (PMID 39062921, 2024). "RKO (RKO-ctr) colon cancer cells and their derivatives undergoing stable small interference (si) RNA for HIPK2 protein (RKO-siHIPK2) with acquisition of pro-invasive capacity were used." (PMID 37892171, 2023). "In human RKO colon cancer cells harboring wt-HIPK2 (HIPK2+/+), cell death was induced, mainly due to c-Jun NH2-terminal kinase (JNK) activation upon glucose starvation." (PMID 25821797, 2015). "We show that HIPK2 knockdown in colon cancer cells resulted in cyclooxygenase-2 (COX-2) upregulation and COX-2-derived PGE2 generation." (PMID 23144866, 2012). "In agreement, tumor xenografts established from colon cancer cells depleted of HIPK2 function, compared to control ones, showed that HIPK2 knockdown increases tumor vascularity and blood density, as evaluated by immunohistochemical analysis and by HIF-1α and VEGF up-regulation at the mRNA levels." (PMID 39062921, 2024). "HIPK2 is downregulated by hypoxia and by hyperglycemia (the latter being a common feature of diabetes mellitus), two conditions often present in solid tumors, including colon cancer, and having a role in cancer progression and resistance to therapies." (PMID 39062921, 2024).
colon carcinoma (continued). "HIPK2 mRNA levels were found to be significantly lower in colon cancer tissues of patients with sporadic colorectal cancer, expressing cytosolic phospholipase A2 (cPLA2), compared to tissues of patients with familial adenomatous polyposis, which showed undetectable cPLA2 levels." (PMID 39062921, 2024). "In agreement with earlier studies, HIPK2 reduction in colon cancer tissues, compared to the normal tissues, could be considered a potential novel prognostic marker of colon cancer progression, along with high production of exomiR-1229." (PMID 39062921, 2024). "Therefore, the authors concluded that HIPK2 protein expression is associated with chemo-response in early-stage colon cancer, which represents an initial step toward defying a novel predictive marker for patients with stage II colon cancer who may benefit from adjuvant therapy." (PMID 39062921, 2024). "In summary, the collected findings indicate that HIPK2 expression could be a useful biomarker to evaluate colon cancer progression and response to therapies, also along with the molecule pathways that interact with it, as summarized above." (PMID 39062921, 2024). "Exosomal miR-1229 derived from HCT-116 colon cancer cells or from blood samples of patients with CRC triggers angiogenesis by targeting the Ser/Thr kinase HIPK2 (Homeodomain Interacting Protein Kinase 2), which acts as either a corepressor or a coactivator of transcription factors." (PMID 36831450, 2023). "This review provides information, mostly with pre-clinical evidence, about a potential candidate biomarker (HIPK2), that might aid in improving the diagnosis and help extend the treatment options of colon cancer cases, thus ameliorating the prognosis of colon cancer patients." (PMID 39062921, 2024). "The purpose of our investigation was to evaluate, in colon cancer and glioblastoma cell lines, whether HIPK2 might inhibit HIF-1α expression and activity in hypoxia-mimicking condition and sensitize chemoresistant tumor cells to adriamycin (ADR)-induced apoptosis." (PMID 19128456, 2009). "SRSF3 regulates alternative splicing of HIPK2 exon 8 to prevent HIPK2-related apoptosis 114, but increases the production of anti-apoptotic protein BCL2 in colon cancer cells." (PMID 37416784, 2023). "In vitro studies using the CRISPR/Cas9 technology confirmed that, compared with Ctrl-Cas9 cells, HIPK2-knockout significantly decreases cell sensitivity to 5-Fluorouracil (5-FU) and oxaliplatin (OXA), drugs frequently used in the treatment of colon cancer, including stage II cases." (PMID 39062921, 2024). "The antitumor activity of both copper complexes as well as that of the free ligand saccharine has been tested in the RKO colon cancer cell line with or without HIPK2 (homeodomain-interacting protein kinase 2) expression." (PMID 37892171, 2023). "In vitro studies with colon cancer cells showed that HIPK2 binds, along with HDAC1, to the HIF-1α gene promoter repressing the HIF-1-mediated transcription of VEGF, in line with data showing that the HIPK2/HDAC1 complex leads to histone deacetylation and control of gene transcription." (PMID 39062921, 2024).
colon carcinoma (continued). "Therefore, colon cancer progression and resistance to therapies may worsen, not only in the presence of chronic inflammatory diseases such as inflammatory bowel disease (IBD), obesity or hyperglycemia, but also by an inflammatory phenotype induced by genetic or epigenetic changes of HIPK2." (PMID 39062921, 2024).